CRP (C-reactive protein)
Diseases named in the same sentence as CRP in open-access papers (continued):
Sharing a sentence is not in itself a finding about the gene and the disease.
psoriasis (continued). "The CRP and PLR might act as biomarkers reflecting the treatment response to TNF-α inhibitors in patients with psoriasis." (PMID 36769622, 2023). "A study of 186 patients with PsV and 50 patients with PsA revealed that NLR and PLR levels decreased in parallel with CRP in Japanese psoriasis patients, regardless of the type of biologic therapy used." (PMID 37109382, 2023). "The A allele was identified to be the “risk allele” related to not only elevated BMI and hip and waist circumference measurements, but also to a higher PASI index (Psoriasis Area Severity Index), CRP (C-reactive protein) values, and serum insulin concentrations." (PMID 35806402, 2022). "PASI—psoriasis area and severity index; RBC—red blood cells; PLT—platelets; WBC—white blood cells; TGs—triglycerides; HDL—high-density lipoproteins; LDL—low-density lipoproteins; CRP—C-reactive protein; ALT—alanine transaminase; ASPAT—asparagine transaminase." (PMID 35888704, 2022). "As expected, participants with psoriasis had higher baseline CRP than participants without psoriasis (p < 0.001), although this difference was borderline significant when we only examined depressed participants (p = 0.056)." (PMID 36471870, 2022). "In our study, we identified a negative correlation between CRP and sTLR2 in psoriasis patients with MetS." (PMID 36556186, 2022). "But for both psoriasis and IBD, we observed trends toward higher CHD risk in those with higher CRP levels, although this numerically higher risk did not meet statistical significance." (PMID 34859072, 2021). "C‐reactive protein (CRP) was significantly correlated with BMI (r = .449, P < .001), LDL‐C (r = .240, P = .026), TG (r = .244, P = .024), and VLDL‐C (r = .241, P = .025) in patients with psoriasis." (PMID 32896023, 2021). "In patients with moderate-to-severe psoriasis treated with systemic therapies, including adalimumab, etanercept, infliximab, and ixekizumab, studies have reported reductions in erythrocyte sedimentation rate (ESR) and/or CRP levels." (PMID 34829740, 2021). "In contrast to CRP or ESR, less is known about the clinical usefulness of SAA in psoriasis." (PMID 32711928, 2020). "In the present study, CRP, MHR, NLR, and MLR were higher in patients with psoriasis than controls." (PMID 31889591, 2020). "The data show that high sensitivity C-reactive protein, serum amyloid A, erythrocyte sedimentation rate, neutrophil-to-lymphocyte ratio, and monocyte to HDL cholesterol ratio can be used as markers of systemic inflammation in patients with psoriasis." (PMID 32711928, 2020). "Another study of 115 adults with psoriasis and 60 matched controls found that EAT as measured by transthoracic echocardiography was higher in the psoriasis group and also found that high-sensitivity CRP was higher in the psoriasis group." (PMID 31795098, 2019). "Chemerin was linearly correlated to CRP and resistin, but not with psoriasis severity measured with PASI or body surface area (BSA)." (PMID 31275060, 2019). "The authors found that CRP levels correlate with PASI and concluded that CRP could be used to assess the severity of psoriasis and to monitor the response to treatment." (PMID 29619128, 2018). "1,25(OH)D, 1,25-hydroxyvitamin D or calcitriol; 25OHD, 25-hydroxyvitamin D; BMI, body mass index; CRP, C -reactive protein; IL, interleukin; MetS, metabolic disease; PASI, psoriasis area and severity index; RDAs, recommended dietary allowances; TNF, tumor necrosis factor; VDR, vitamin D receptor." (PMID 28176237, 2017). "The white blood cell count and C-reactive protein measures of general health status were lower for those with psoriasis, although none were statistically significant." (PMID 28496169, 2017). "In our study, the white blood cell count and C-reactive protein measures of general health status were lower for those with psoriasis, although no statistically significant." (PMID 28496169, 2017).
psoriasis (continued). "In addition, we found significant correlations between PhA with the clinical severity of psoriasis, expressed by PASI score and CRP levels, and the quality of life in these patients, independently of BMI." (PMID 27165166, 2016). "In addition, we found significant correlations between PhA with the clinical severity of psoriasis, expressed by PASI score, CRP levels, and the quality of life in these patients, independently of BMI." (PMID 27455297, 2016). "One other common link in the inflammatory cascade of psoriasis and CVD may be C-reactive protein (CRP)." (PMID 27448600, 2016). "They included erythrocyte sedimentation rate (ESR), C-reactive protein (CRP), visual analogue scale (VAS), Health Assessment Questionnaire (HAQ) modified for Spondyloarthritis, Psoriasis Area Severity Index (PASI) score, the 28-joint Disease Activity Score (DAS 28), and US-PD assessment." (PMID 22649467, 2012). "Indeed, psoriasis patients with depression exhibit higher systemic inflammation markers, including C-reactive protein and erythrocyte sedimentation rate, compared to non-depressed psoriasis patients." (PMID 40428224, 2025). "Finally, CRP levels were significantly higher in patients with psoriasis and metabolic syndrome compared to those without." (PMID 40584532, 2025). "However, correlation analysis revealed that psoriasis presence did not significantly correlate with inflammatory biomarkers such as ROS (r = 0.08, p = 0.21), CRP (r = 0.11, p = 0.12), TNF-α (r = 0.09, p = 0.18), or IL-6 (r = 0.07, p = 0.23)." (PMID 41216079, 2025). "Nevertheless, it is found that statin improves psoriasis symptoms due to its immunomodulatory and anti-inflammatory effect through the inhibition of leukocyte function antigen-1 (LFA-1), interleukin-1 and -6, and tumor necrotic factor alpha (TNF-α), and its ability to reduce CRP levels." (PMID 39120229, 2024). "Moreover, there was highly statistically significant difference in serum CRP and TNFα levels between responders and non-responders in psoriasis patients as regards PASI 50 (P < 0.0001)." (PMID 38965465, 2024). "Moreover, there was highly statistically significant variance in serum CRP and TNFα levels between responders and non-responders in psoriasis patients as regards PASI 50 (P < 0.0001)." (PMID 38965465, 2024). "Thus, patients undergoing systemic treatment with biotherapies and with methotrexate, respectively, exhibited significantly lower CRP values (p=0.000091 and p=0.009, respectively) than patients with psoriasis without treatment." (PMID 38046733, 2023). "Additional and more extensive studies would be needed at this point to establish whether RDW or not might be a biomarker of inflammation in patients with psoriasis that is not reflected by the PASI score or CRP." (PMID 33776570, 2021). "All the parameters studied (CRP, MHR, NLR, PLR, and MLR) were positively correlated with PASI scores, which leads to the suggestion that these parameters may be used during the follow-up of psoriasis." (PMID 31889591, 2020). "Moreover, MHR and CRP levels were positively correlated, which leads to the suggestion that MHR might be a reliable marker of systemic inflammation in psoriasis." (PMID 31889591, 2020). "The lack of a robust CRP signal in psoriasis and PsA is owed to the fact that interleukin (IL)-6, the essential stimulator of CRP, plays no critical role in these diseases, which is illustrated by the very limited therapeutic effect of IL-6 neutralization in psoriatic disease." (PMID 32051028, 2020). "Lack of CRP, however, does not mean that systemic inflammation is absent but rather indicate that different markers are needed that allow better quantification of systemic inflammation in psoriasis and PsA." (PMID 32051028, 2020). "Since CRP is a well-accepted marker of inflammation, it may be hypothesized that among the studied parameters, MHR tends to be more reliable in indicating the inflammatory status in psoriasis." (PMID 31889591, 2020).
psoriasis (continued). "The authors found higher levels of highly sensitive CRP (hsCRP), osteoprotegerin (OPG), and MMP-3 in patients with psoriasis and psoriatic arthritis as compared to patients with psoriasis alone and concluded that these could be biomarkers for psoriatic arthritis in patients with psoriasis." (PMID 29619128, 2018). "Additionally, a negative and significant correlation was found between CRP values and disease duration in psoriasis patients." (PMID 29967791, 2018). "However, although PTX3 does not seem to be related to CRP in psoriasis, it is reportedly positively related to the extent and severity of skin psoriasis." (PMID 28225768, 2017). "This could either support the notion that CRP is not a reliable complementary test to PASI in regard to the evaluation of the severity of psoriasis, or that its utility in the clinical setting is limited only to the evaluation of the immediate level of systemic inflammation." (PMID 35625870, 2022). "Moreover, high sensitivity C-reactive protein, serum amyloid A, monocyte to HDL cholesterol ratio and lymphocyte-to-monocyte ratio are closely related to the Psoriasis Area and Severity Index score, and they may be regarded as objective indicators in determining the disease severity." (PMID 32711928, 2020). "In contrast, in patients with severe psoriasis, significant negative correlations of PON1 with CRP and AST activity were observed." (PMID 35888704, 2022). "Patients with psoriasis and NMSC showed statistically significant higher plasma NGAL, MMP-9, and CRP levels compared to patients with psoriasis without skin cancers." (PMID 36293148, 2022). "Patients with psoriasis and NAFLD were also more likely to have higher circulating levels of C-reactive protein, IL-6 and lower adiponectin levels than those without NAFLD." (PMID 26861300, 2016). "Interestingly, the well-established markers for systemic inflammation CRP and WBC showed no intraindividual correlation with PASI during a 4-month time course of systemic therapy in psoriasis patients." (PMID 38127137, 2024). "In turn, in patients with long-lasting psoriasis (>20 years, n = 16) negative correlations between gal-3 levels and total cholesterol and triglycerides levels were noted, and positive ones with PASI, CRP, and ALT activity." (PMID 35053087, 2022). "Systemic inflammation (increased CRP level), prediabetes, and aging may influence enhanced AGE accumulation in patients with psoriasis without any comorbidities." (PMID 30363704, 2018). "Serum total CER concentration did not correlate with the psoriasis severity measured by PASI, time of the duration of the disease nor the investigated laboratory results: C-reactive protein, white blood cell count, platelet count, fasting glucose, vitamin D concentration." (PMID 27988894, 2017). "Similarly, another case-control study, which included 37 patients, showed that selenium supplementation as add-on treatment to narrowband UVB therapy did not significantly improve psoriasis severity (assessed by PASI score) and TNF-R1 and CRP concentrations compared to placebo." (PMID 33499118, 2021).
chronic obstructive pulmonary disease (265 papers, 2005 to 2026). A chronic and progressive lung disorder characterized by the loss of elasticity of the bronchial tree and the air sacs, destruction of the air sacs wall, thickening of the bronchial wall, and mucous accumulation in the bronchial tree. "In this study, lung diseases (asthma and chronic obstructive pulmonary disease) were associated with higher CRP levels." (PMID 39852142, 2025). "CHIP has been associated with increased levels of C-reactive protein, chronic obstructive pulmonary disease, and vasculitis." (PMID 36184726, 2023). "Using PheWAS analysis in the UKB, we identified a potentially causal association between genetically elevated CRP and risk of chronic airway obstruction." (PMID 35459240, 2022). "Phenome-wide association study identified 27 clinical outcomes associated with genetically determined CRP and subsequent Mendelian randomisation analyses supported a causal association with schizophrenia, chronic airway obstruction and prostate cancer." (PMID 35459240, 2022). "Heparin-binding protein, white blood cells, CRP, etc. have diagnostic and predictive value for acute exacerbation of chronic obstructive pulmonary disease." (PMID 35024012, 2021). "Elevated circulating levels of C-reactive protein (CRP), interleukin (IL)-6 and fibrinogen (FG) have been repeatedly associated with many adverse outcomes in patients with chronic obstructive pulmonary disease (COPD)." (PMID 19272152, 2009). "The presence of consolidation on CXR, comorbid cardiovascular and chronic obstructive pulmonary diseases, high body temperature, and increased serum aspartate aminotransferase, potassium, and C-reactive protein levels were independent risk factors for rapid deterioration of CXR findings." (PMID 38086863, 2023). "Finally, support for potential causality of low-grade chronic inflammation marked by CRP on risk of schizophrenia, chronic airway obstruction and prostate cancer highlights avenues of disease prevention through modulation of inflammation." (PMID 35459240, 2022). "In addition, a positive association was observed between CTRP5 and C-reactive protein (CRP) in subjects with chronic obstructive pulmonary disease." (PMID 29964236, 2019). "They found that in patients with chronic obstructive pulmonary disease, elevated levels of inflammatory biomarkers (CRP, fibrinogen, and leukocyte count) were associated with an increased risk of PExs, even in those with mild chronic obstructive pulmonary disease." (PMID 28066689, 2016). "Using polygenic risk scores of serum CRP and the design of Mendelian randomization, the genetic propensity to higher serum CRP was associated with a reduced risk of schizophrenia and prostate cancer, as well as an increased risk of chronic obstructive pulmonary disease." (PMID 37493001, 2023). "High CRP levels were associated with younger age, higher body mass index (BMI), chronic obstructive pulmonary disease (COPD), lower peak oxygen consumption and higher endothelin-1 and aldosterone levels." (PMID 30114262, 2018). "Among both healthy individuals and chronic obstructive pulmonary disease (COPD) patients, an inverse association between blood levels of fibrinogen and C-reactive protein (CRP) and forced expiratory volume in 1 second (FEV1) has been reported." (PMID 20625390, 2010). "Biomarkers such as C-reactive protein (CRP) and cytokines also appear to predict the development and outcomes of cardiac arrhythmias." (PMID 39301907, 2025). "There were statistically significant differences in CRP levels between patients with a history of pulmonary disease (asthma or chronic obstructive pulmonary disease) and the rest of the patients." (PMID 39852142, 2025). "More recently, researchers developed a wireless patch for the real-time electrochemical detection of the CRP in sweat and assessed the evaluation in patients with chronic obstructive pulmonary disease." (PMID 39499914, 2024).
chronic obstructive pulmonary disease (continued). "Another study sought to determine how high-dose vitamin D (300,000 IU) supplementation affected systemic inflammatory biomarkers (IL-6, IL-8, CRP) in patients with chronic obstructive pulmonary disease experiencing acute exacerbation." (PMID 37375645, 2023). "For instance, in chronic obstructive pulmonary disease, the ACE I/D polymorphism was associated with high CRP levels." (PMID 37238156, 2023). "For example, chronic obstructive pulmonary disease, smoking-related lung diseases, and the progression of atherosclerotic lesion would have led to the elevated CRP levels, affecting the results." (PMID 37686634, 2023). "In cases of chronic obstructive pulmonary disease exacerbations, higher CRP levels are observed in bacterial infections involving Haemophilus influenzae and Streptococcus pneumoniae." (PMID 38188635, 2023). "Evidence shows that CRP testing reduce antibiotic prescribing for patients with acute RTIs and acute exacerbations of chronic obstructive pulmonary disease in primary care." (PMID 35485789, 2022). "Elevated N/L has been used as a marker in the determination of increased inflammation in acute exacerbations of chronic obstructive pulmonary disease, which is similar to C-reactive protein." (PMID 34786313, 2021). "From the biomarkers, C-reactive protein and d-dimer were more elevated among the cardiac arrhythmia group." (PMID 35070544, 2021). "A study in general practice found a reduction of antibiotics in patients with chronic obstructive pulmonary disease by using CRP levels, but this finding needs confirmation in a nursing home setting." (PMID 34548288, 2021). "Despite divergent data from various studies, CRP is used to assess acute exacerbations of chronic obstructive pulmonary disease or infectious complications of malignancies in order to reduce the use of antibiotics." (PMID 32731610, 2020). "The risk of events was in fact directly related to the occurrence of sustained post-operative cardiac arrhythmias, higher values of NT-proBNP and of arterial PH, and inversely related to values of CRP." (PMID 33510881, 2020). "The strongest predictors included Sex, DM history, anastomotic type, reconstruction route, smoking history, CRP level and presence of cardiac arrhythmia." (PMID 32252738, 2020). "We analyzed differential expression and methylation as well as expression according to patient characteristics like smoking status, histology, age, chronic obstructive pulmonary disease, C-reactive protein (CRP) and gender." (PMID 30016964, 2018). "MSC treatment of chronic inflammatory diseases in human, such as chronic obstructive pulmonary disease, induces suppression of serum CRP." (PMID 27575050, 2016). "Matrix metalloproteinases (MMPs) and C-reactive protein (CRP) are involved in chronic obstructive pulmonary disease (COPD) pathogenesis." (PMID 24980707, 2014). "In summary, our study confirms that C-reactive protein levels are increased in stable chronic obstructive pulmonary disease patients." (PMID 24073993, 2013). "RBP4 was positively correlated with creatinine and body mass index, and negatively correlated with C-reactive protein and Global Initiative for Chronic Obstructive Lung Disease stage." (PMID 24099047, 2013). "Moreover, the use of a KS disaccharide L4 suppressed lipopolysaccharide-induced lung inflammation in mice in a model of chronic obstructive pulmonary disease, a disease in which CRP levels are generally significantly elevated." (PMID 41614767, 2025). "SLD, steatotic liver disease; COPD, chronic obstructive pulmonary disease; BMI, body mass index; CRP, C-reactive protein; AST, aspartate aminotransferase; ALT, alanine aminotransferase; ALP, alkaline phosphatase; GGT, gamma-glutamyltransferase; INR, international normalized ratio." (PMID 38731216, 2024).